MEOX1 (mesenchyme homeobox 1)
Diseases named in the same sentence as MEOX1 in open-access papers (continued):
Sharing a sentence is not in itself a finding about the gene and the disease.
Myocardial fibrosis (3 papers, 2022 to 2024). "Lastly, the induction of myocardial fibrosis after acute myocardial infarction is attributed to the action of MEOX1 through the process of EndoMT." (PMID 38431730, 2024). "MEOX1, linked to the TGF-β signaling pathway, appears to facilitate myocardial fibrosis via EndoMT following AMI." (PMID 38431730, 2024). "Several therapeutic targets for myocardial fibrosis, such as Ddah1, Meox1, and Ctrhc1, have been identified by single cell sequencing analysis and have provided novel theoretical targets for the treatment of myocardial fibrosis." (PMID 35799890, 2022). "Given the significant interstitial fibrosis in these areas, we hypothesize that MEOX1 may instigate myocardial fibrosis post-acute myocardial infarction via EndoMT." (PMID 38431730, 2024). "Runx1 expression was also observed in cardiac fibroblasts along with genes contributing to myocardial fibrosis, such as POSTN, MEOX1 and FAP, and its expression was also negatively correlated to ejection fraction." (PMID 38862712, 2024). "Immunofluorescence analysis confirmed the presence of high MEOX1 and α-SMA expression in these tissues, suggesting a significant positive correlation between MEOX1 expression and myocardial fibrosis post-AMI." (PMID 38431730, 2024).
myocardial infarction (3 papers, 2022 to 2026). Gross necrosis of the myocardium, as a result of interruption of the blood supply to the area, as in coronary thrombosis. "Consequently, in order to delve deeper into the potential implications of MEOX1 upregulation in AMI, we undertook a rat model of myocardial infarction to authenticate the impact of MEOX1 on AMI in vivo, as well as to investigate the underlying mechanisms." (PMID 38431730, 2024). "Following myocardial infarction, MEOX1 expression is predominantly observed in the microvascular endothelium of the infarct and peri-infarct myocardium RT-qPCR." (PMID 38431730, 2024). "This study has identified several key findings: Firstly, MEOX1 has consistently been found to be differentially expressed in both the dataset of acute myocardial infarction and the TGFβ signaling pathway." (PMID 38431730, 2024). "However, a comprehensive understanding of MEOX1's expression and biological function in the context of acute myocardial infarction is lacking, particularly concerning its role in immune infiltration and endothelial-mesenchymal transition following myocardial infarction." (PMID 38431730, 2024). "However, once fibroblasts become activated or the heart suffers injury (e.g., myocardial infarction), fibroblasts may also strongly express other markers such as periostin (POSTN), alpha smooth muscle actin (αSMA) or mesenchyme homeobox 1 (MEOX1), among other genetic signatures." (PMID 35548426, 2022).
cardiac hypertrophy (2 papers, 2022 to 2026). "Our identification of the mmu-Lrrc2_0005---miR-92a-2-5p---Meox1 axis may serve as a novel mechanism by which Meox regulates cardiac hypertrophy." (PMID 36003513, 2022).
heart failure (2 papers, 2024 to 2026). Inability of the heart to pump blood at an adequate rate to meet tissue metabolic requirements. "From the perspective of clinical translation, targeting Meox1/Cthrc1/p-Smad2/3 axis offers novel therapeutic potential for treating heart failure and improving the outcomes in patients with MI." (PMID 41362745, 2026). "From the clinical translational perspective, the present study suggests that Meox1/Cthrc1/p-Smad2/3 signaling pathway is a promising prognostic and therapeutic target for post-MI cardiac fibrosis and heart failure." (PMID 41362745, 2026). "Taken together, our results demonstrated that inhibiting Meox1/Cthrc1/p-Smad2/3 signaling suppressed CFs-to-Myofbs conversion and prevented fibrotic remodeling and heart failure, which may provide clinical translational implications for improving the prognosis of MI patients." (PMID 41362745, 2026).
intrahepatic cholangiocarcinoma (2 papers, 2023). A carcinoma that arises from the intrahepatic bile duct epithelium in any site of the intrahepatic biliary tree. "However, despite the importance of MEOX1 in both development and cancer, only recently a first report has indicated MEOX1 to be important for Treg cells in the context of the tumor environment in intrahepatic cholangiocarcinoma and the acquisition of a tumor-infiltrating Treg cell phenotype." (PMID 37559728, 2023).
non-small cell lung carcinoma (2 papers, 2023 to 2025). A group of at least three distinct histological types of lung cancer, including non-small cell squamous cell carcinoma, adenocarcinoma, and large cell carcinoma. "Endothelial cells play a critical role in tumor-associated vasculature formation and immune modulation, and dysregulation of transcription factors (TFs) such as Meox1 has been associated with various cancers, including non-small cell lung cancer (NSCLC)." (PMID 40919158, 2025). "Furthermore, MEOX1 has been implicated in the development and progression of breast and non-small cell lung cancer." (PMID 37559728, 2023). "To investigate the expression of MEOX1 in more detail, we reanalyzed a recently published single-cell RNA-seq dataset that comprised human CD4+ and CD8+ T cell populations from non-small-cell lung cancer patients." (PMID 37559728, 2023).
triple-negative breast carcinoma (2 papers, 2023 to 2024). An invasive breast carcinoma which is negative for expression of estrogen receptor (ER), progesterone receptor (PR), and human epidermal growth factor receptor 2 (HER2).
dermatofibrosarcoma protuberans (1 paper, 2024). Dermatofibrosarcoma protuberans (DFSP) is a rare infiltrating soft tissue sarcoma, generally of low grade malignancy, arising from the dermis of the skin and characteristically associated with a specific chromosomal translocation t(17;22). "Dermatofibrosarcoma protuberans is an aggressive spindle cell neoplasm that is known for its expression of MEOX1." (PMID 38486335, 2024).
epilepsy (1 paper, 2021). A brain disorder characterized by episodes of abnormally increased neuronal discharge resulting in transient episodes of sensory or motor neurological dysfunction, or psychic dysfunction. "Subject 7 had a de novo PDV in MEOX1 along with connective tissue defects, congenital malformations, epilepsy, and neuropsychiatric behavior developmental phenotypes." (PMID 33562221, 2021).
Hepatic fibrosis (1 paper, 2025). The presence of excessive fibrous connective tissue in the liver. "Taken together, we firstly demonstrated that MEOX1-regulated circABHD3 exacerbated hepatic fibrosis via promoting EMT and mitochondrial through suppression of YPEL3-mediated inactivation of β-catenin signaling in a YTHDF2-dependent manner." (PMID 40100806, 2025). "Given the significant involvement of MEOX1 in fibrosis, we examined MEOX1 expression in hepatic fibrosis tissues from patients." (PMID 40100806, 2025). "MEOX1 was highly expressed, and its expression was positively correlated with circABHD3 expression in hepatic fibrosis tissues (Fig 3Aand3B)." (PMID 40100806, 2025). "MEOX1-mediated generation of circABHD3 promotes EMT and mitochondrial impairment by enhancing YTHDF2-mediated degradation of YPEL3 mRNA and activating downstream β-catenin signaling, thus exacerbating hepatic fibrosis." (PMID 40100806, 2025).
Hirsutism (1 paper, 2023). Abnormally increased hair growth referring to a male pattern of body hair (androgenic hair). "We found several differences in newborn methylation at individual CpG probes by maternal PCOS with reported hirsutism, though the difference in methylation near the DACT2 and MEOX1 genes may be due to downstream genetic control." (PMID 37992405, 2023).
hyperlipidemia (1 paper, 2022). "Cluster 1 represents a distinct population of cells expressing genes involved in inflammation (Ifi27l2a), hyperlipidemia (Gata4), VSMC phenotypic modulation (Meox1), calcification and bone formation (Htra4, Meox1)." (PMID 35163719, 2022).
serous ovarian adenocarcinoma (1 paper, 2024). "Bioinformatic analyses revealed that serous ovarian adenocarcinoma had the highest level of MEOX1 expression compared to other histopathological subtypes." (PMID 38486335, 2024).
Stroke (1 paper, 2020). Sudden impairment of blood flow to a part of the brain due to occlusion or rupture of an artery to the brain. "In addition, mesenchyme homeobox 1 (Meox1), placental growth factor (pgf) and insulin-like growth factor binding protein 4 and 5 (Igfpb4 and 5) were among the genes associated with angiogenesis and upregulated following stroke." (PMID 32848875, 2020).
cancer (13 papers, 2012 to 2026). A tumor composed of atypical neoplastic, often pleomorphic cells that invade other tissues. "MEOX1 plays key role in regulating somite development, which associated with cancer progression." (PMID 31464612, 2019). "A murine LLC cancer model was employed to investigate the effect of Meox1 consumption on PD-1/PD-L1 blockade therapy." (PMID 40919158, 2025). "Firstly, we utilized the University of ALabama at Birmingham Cancer Data Analysis Portal (UALCAN) to analyze the median mRNA expression of MEOX1 in tumor tissues." (PMID 38486335, 2024). "Of note, previous studies have identified Meox1 as a target for cancer stem cell treatment; yet, its role in marking growth-specific stem cells in zebrafish was only recently reported." (PMID 38732090, 2024). "Through pan-cancer analysis, we discovered that MEOX1 expression was generally lower in tumor tissues of most cancer types compared to corresponding normal tissues, such as BRCA and LUSC, which was not fully aligned with previous reports." (PMID 38486335, 2024). "In our study, we investigated the expression of MEOX1 in various cancer types using different databases." (PMID 38486335, 2024). "Within the cancer cells nuclear protein localization of MEOX1 was correlated with poorer overall survival, an advanced tumor stage, and the presence of lymph node metastasis." (PMID 27285982, 2016). "Although MEOX1 is well-established as one of the key transcriptional regulators during embryonic development, our results demonstrate that MEOX1 is also involved in cancer development through participating in the PBX1 transcriptional network." (PMID 22567123, 2012). "Based on this rationale, we performed a “rescue” assay by ectopically expressing MEOX1 in cancer cells with PBX1 knockdown." (PMID 22567123, 2012). "Another exciting finding in this study is the identification of a new role of MEOX1 in cancer pathogenesis." (PMID 22567123, 2012). "In addition, Meox1 also promoted the invasion, proliferation and metastasis of tumor cells, eventually accelerating the malignant progress of various cancers 19-21." (PMID 41362745, 2026). "Next, we investigated the expression of MEOX1 in tumor tissues and matched normal tissues of various TCGA cancer types using two databases: Tumor Immune Estimation Resource Version 2 (TIMER2.0) and Gene Expression Profiling Interactive Analysis version 2 (GEPIA2.0)." (PMID 38486335, 2024). "Moreover, we found that MEOX1, as a transcription factor, was primarily localized in the nucleus of cancer cells, with minimal expression in the tumor matrix." (PMID 38486335, 2024). "The preceding research indicates that MEOX1 may be a new target for the occurrence and progression of tumor, but its function in cancer is heterogeneous." (PMID 38486335, 2024). "It is worth noting that many other genes may also be involved in EMT and MET, which require further investigation; but MEOX1 was one of the most specifically upregulated genes within mesenchymal cancer cells in this study." (PMID 27285982, 2016). "Interestingly, cytoplasmic expression of MEOX1 was present in the majority of tumors but limited particularly to cancer cells." (PMID 27285982, 2016). "While the role of MEOX-1 in cancer has largely been unexplored, one study by Thiaville et." (PMID 27285982, 2016). "Given the importance of proliferation and invasion in cancer progression, we tested whether inhibiting the expression of MEOX1 in BT474 PTEN- LTT cells could affect cell growth by MTS assay and invasion into matrigel." (PMID 27285982, 2016). "For more than half of the MES and ADRN TFs (e.g., SIX1, MEOX1, and ZNF536), decreased cumulative survival was observed for two cancer types in particular; KIRP and UCEC, but to a lower extent in other cancers, indicating the influence of these TFs on patient survival in these cancers." (PMID 35201514, 2021).
tumor (13 papers, 2016 to 2026). "While our data strongly implicate CD8+ T-cell cytotoxicity as a primary mediator of Meox1 knockdown-driven tumor control, definitive causal evidence through T-cell depletion requires further investigation." (PMID 40919158, 2025). "While Meox1 is recognized as a pivotal regulator in tumor-associated endothelial cells, its molecular underpinnings remain undefined." (PMID 40919158, 2025). "MEOX1 overexpression reprograms Tregs to acquire a transcriptional profile associated with tumor infiltration." (PMID 37164005, 2023). "Meox1 has been implicated in promoting both tumor-promoting and immune-suppressing functions." (PMID 40919158, 2025). "While most studies have focused on embryonic development, recent research has shown that MEOX1 is abnormally expressed in various tumor tissues and contributes to various phenotypes associated with tumor progressions, such as tumor proliferation, metastasis, and chemoresistance." (PMID 38486335, 2024). "In the current study, our findings demonstrated that the transcription factor Meox1 is a persistent regulator of tumor angiogenesis." (PMID 40919158, 2025). "The results indicate that Meox1 knockdown promotes tumor vascular normalization, facilitating the entry of immune cells into tumors to kill tumor cells." (PMID 40919158, 2025). "Quantitative analysis revealed pronounced Meox1 transcript depletion (p<0.0001) in siRNA-perfused tumor regions." (PMID 40919158, 2025). "Consistent with this, IHC staining for GzmB revealed elevated GzmB+ cell numbers in propionate-treated tumours, which were significantly reduced upon Meox1 knockdown." (PMID 40715695, 2025). "In this study, Meox1 deletion at the beginning of tumor growth consistently diminished tumor progression." (PMID 40919158, 2025). "Measurement of subcutaneous tumour weight revealed that intratumoral injection of Meox1 siRNA significantly attenuated propionate-induced radiosensitisation in IRT." (PMID 40715695, 2025). "Here we report that the complete TFs landscape within the LLC tumor immune microenvironment, uncovering Meox1’s dual role in driving tumor angiogenesis and reducing CD8+ T-cell infiltration." (PMID 40919158, 2025). "Genetic ablation of Meox1 suppresses tumor growth through an anti-angiogenic mechanism, where vascular normalization improves intertumoral drug penetration." (PMID 40919158, 2025). "Our data establish Meox1 as a critical transcriptional regulator that mechanistically links tumor neovascularization to malignant progression." (PMID 40919158, 2025). "Real-time qPCR analysis of tumour tissues revealed that propionate treatment significantly upregulated the transcriptional levels of Meox1, Cxcr6, and Ccl5, whereas Meox1-siRNA administration abolished these effects." (PMID 40715695, 2025). "qPCR analysis of tumours from each group revealed that Pknox2, Irf4, Pou3f1, Cebpb, and Meox1 were significantly upregulated by propionate and B. fragilis." (PMID 40715695, 2025). "This population was found to be closely correlated with the presence of the transcription factor mesenchyme homeobox 1 (MEOX1) in tumor cells." (PMID 38213535, 2023). "MEOX1 cytoplasmic staining was positive in 105 primary tumors (top), whereas nuclear staining was positive in 72 tumor samples (bottom)." (PMID 27285982, 2016). "Taken together these results provide a proof of concept that inhibition of MEOX1 using a small molecule is a feasible approach to inhibit BCSCs and bulk tumor growth in vivo." (PMID 27285982, 2016). "Along with the accompanied MEOX1 downregulation, SF significantly reduced tumor volume by 54% (left, p-value=0.028) in the BT474-PTEN-LTT xenograft model whereas no inhibitory effect was observed in BT474 xenografts." (PMID 27285982, 2016). "Interestingly, mice treated with Meox1 siRNA alone exhibited significantly retarded tumor progression compared with the control group." (PMID 40919158, 2025).
tumor (continued). "Furthermore, we reveal the dual role of Meox1 in driving tumor angiogenesis and suppressing CD8+ T cell infiltration, thereby establishing its therapeutic implications for overcoming immunotherapy resistance." (PMID 40919158, 2025). "In summary, it can be hypothesized that MEOX1 may influence lymph node metastasis by regulating tumor growth, tumor EMT, ECM degradation, and lymphangiogenesis." (PMID 38486335, 2024). "Notably, we observed a higher protein level of MEOX1 in tumor tissues of LNM-positive HGSOC compared to LNM-negative HGSOC." (PMID 38486335, 2024). "Moreover, the researchers discovered that targeted enrichment of MEOX1 can induce a reprogramming effect on circulating Tregs, leading them to acquire the transcriptional and epigenetic characteristics observed in tumor-infiltrating Tregs." (PMID 38213535, 2023). "Reduced level of MEOX1 by siRNA or small molecule inhibitor could decrease mammosphere and colony formation in vitro, and decreased tumor growth and BCSC frequency in vivo." (PMID 27285982, 2016). "With a recently published report of MEOX1 being important for the acquisition of a tumor-infiltrating Treg cell phenotype it is conceivable to speculate, that MEOX1 in humans is a key factor for the transcriptional acquisition of a Treg cell effector phenotype downstream of IL-2 signaling." (PMID 37559728, 2023). "This upregulates the Meox1-Cxcr6/Ccl5 axis, enhances CD8+ T cell infiltration in tumours, and sensitises MSS-CRC to combined radiotherapy and immunotherapy." (PMID 40715695, 2025). "Flow cytometry showed that propionate significantly increased tumour-infiltrating CD8+ T cells, an effect reversed by Meox1 siRNA." (PMID 40715695, 2025). "The knockdown of Meox1 by specific siRNA was found to potentiate the sensitivity of LLC tumors to BMS-1, leading to a dramatically reduction in tumor burden." (PMID 40919158, 2025). "Downregulation of MEOX1 by SF in the BT474 PTEN- LTT cell line in vitro and in an orthotopic mouse xenograft model in vivo was able to effectively inhibit bulk tumor volume and reduce frequency of BCSCs, as evident by ELDA in secondary mice." (PMID 27285982, 2016). "In order to evaluate if the downregulation of MEOX1 was consistent with these observations in vivo, frequency of BCSC and tumor growth in vivo were measured after treatment with sulforaphane (50 mg/kg, I.P)." (PMID 27285982, 2016). "Furthermore, we observed a marked reduction in tumor cell proliferation and an increase in CD8 expression, a marker of T-cell activity in an animal model system, indicating that Meox1 may also play a regulatory role in immune-mediated tumor suppression." (PMID 40919158, 2025). "In brief, these data demonstrate that RNA interference-mediated Meox1 ablation significantly attenuates neoplastic cell proliferation through dual mechanisms involving angiogenic suppression and immunological remodeling through enhanced CD8 cytotoxic T lymphocyte tumor infiltration." (PMID 40919158, 2025).